PADI4 (peptidyl arginine deiminase 4)
Diseases named in the same sentence as PADI4 in open-access papers (continued):
Sharing a sentence is not in itself a finding about the gene and the disease.
gastric cancer (15 papers, 2009 to 2023). A primary or metastatic malignant neoplasm involving the stomach. "This genotyping study encouraged us to focus on the pathogenic mechanism of PADI4 in gastric cancer." (PMID 27556695, 2016). "The increased expression of PADI4 in gastric tumor tissues corresponds to the present finding regarding the significant association of PADI4-encoding DNA variants with gastric carcinoma." (PMID 27556695, 2016). "PADI4 levels also significantly associated with CEA levels in patients with gastric cancer (p = 0.05) and prostate cancer (p = 0.028)." (PMID 19183436, 2009). "Notably, nucleotide variations in the tagged single-nucleotide polymorphisms (SNPs) rs882537 and rs1635566 in the PADI4 locus have been significantly correlated with gastric cancer, suggesting PADI4 is a susceptibility gene for gastric cancer." (PMID 36365233, 2022). "Peptidyl arginine deiminase IV (PADI4) is a susceptibility gene for gastric carcinoma." (PMID 35045833, 2022). "In summary, the present study demonstrated that PADI4 is a susceptible gene of gastric carcinoma." (PMID 27556695, 2016). "Our result indicates that the PADI4 gene has genetic susceptibility in gastric carcinoma." (PMID 27556695, 2016). "Over the years, numerous experts have confirmed that EMT is significantly associated with the metastasis of gastric cancer and can potentially enhance the migratory capability of gastric cancer cells by inducing the upregulation of NFE2L3 or PADI4." (PMID 38149985, 2023). "The protein labeled with IPO-38, a highly sensitive and specific marker for the diagnosis of gastric cancer, is considered to be a member of the histone family and is regulated by citrullination mediated by PADI4 in gastric cancer." (PMID 37777749, 2023). "In gastric cancer, PADI4 can accelerate GC metastasis by promoting IL-8 and can also promote proliferation." (PMID 37020554, 2023). "Some scholars believe that PADI4 promotes the occurrence and development of gastric cancer by up-regulating TNF-α, CXCR2, and KRT14 in MNK-45 cells and SGC 7901 cells." (PMID 37804426, 2023). "PADI4 plays a role in gastric cancer by upregulating the expression of C-X-C motif chemokine receptor 2 (CXCR2), keratin 14 (KRT14), and tumor necrosis factor (TNF-α)." (PMID 37804426, 2023). "In gastric cancer, PADI4 promotes gastric tumorigenesis and angiogenesis by upregulating CXCR2, KRT14, and TNF-α expression." (PMID 37020554, 2023). "Our data suggest that PADI4 accelerate metastasis by promoting IL-8 expression in gastric cancer cells, indicating that it is a new PADI4/IL-8 signalling pathway in metastatic GC." (PMID 35045833, 2022). "Since PADI2 or PADI4 catalyzes the conversion of arginine to citrulline in humans, we examined the protein levels of PADI2, PADI4, and H3R26Cit in several human gastric cancer cell lines." (PMID 31058095, 2019). "Our study clarified that PADI4 is a main regulatory enzyme of histone citrullination, at least in gastric cancer." (PMID 31058095, 2019). "We and others demonstrated marked overexpression of PADI4 in many human cancers, including cervical squamous cell carcinoma, gastric carcinoma, lung cancer, ovarian serous papillary adenocarcinoma and papillary carcinoma of the thyroid." (PMID 27556695, 2016). "Both genotyping methods demonstrated significant associations between the tag SNPs rs1635566 and rs882537 in the PADI4 locus with gastric carcinoma in two independent cohorts." (PMID 27556695, 2016). "PADI4 levels were also significantly associated with CEA levels, a serum marker for tumour diagnosis, in the blood of patients with gastric cancer and prostate cancer." (PMID 20222985, 2010).
gastric cancer (continued). "Our previous studies showed that PADI4 has a molecular weight of 67 kDa in esophageal cancer, 74 kDa in esophageal squamous cell carcinoma, and 74 kDa and 70 kDa in gastric cancer." (PMID 37804426, 2023). "The aim of this study was to evaluate the functional roles of PADI4 in gastric cancer." (PMID 35045833, 2022). "In addition, the functional roles of PADI4 were explored by over-expression PADI4 plasmids in gastric cancer cells." (PMID 35045833, 2022). "In addition, the inhibition of PAD4 expression by PADI4 siRNA resulted in arrest in the S phase and a reduction in the number of gastric cancer cells in the G2/M phase cell number reduction, specifically and significantly reducing the proliferative and invasive capacity of SGC-7901 and AGS cells." (PMID 36365233, 2022). "In addition, PADI4 siRNA therapy together with 5-FU treatment enhanced the siRNA inhibitory effect on gastric cancer cell proliferation, suggesting that this combinatory regimen may help reduce the drug resistance of gastric cancer cells and improve therapeutic efficacy." (PMID 36365233, 2022). "We all know that IL-8 plays a vital role during the process of EMT, and we have found that PADI4 can regulate the expression of IL-8 and participate in the EMT process of gastric cancer." (PMID 35045833, 2022). "In addition, PADI4 has been found to promote the EMT and the migration of gastric cancer cells by up-regulating IL-8." (PMID 37777749, 2023). "Overexpression of PADI4, via transfection of a eukaryotic expression vector, and knockdown of PADI4 gene expression, by a PADI4 CRISPR/Cas9 vector, confirmed the crucial function of PADI4 on the increased level of H3R26Cit in gastric cancer cell lines." (PMID 31058095, 2019).
colorectal cancer (14 papers, 2014 to 2025). A primary or metastatic malignant neoplasm that affects the colon or rectum. "In colorectal cancer cells, GSK3β binds to highly expressed PADI4 and is citrullinated at R344, promoting nuclear translocation of GSK3β from the cytoplasm to nucleus." (PMID 37777749, 2023). "To observe the consequences of PADI4-mediated DNMT3A upregulation specifically, we used the colorectal cancer cell line HCT-116, where both the DNMT1 and DNMT3B DNMTs have been genetically disrupted (DKO cells) and where DNMT activity is minimal." (PMID 24957603, 2014). "In liver metastases of colorectal cancer, the citrullination of ECM proteins mediated by PADI4 can promote MET by enhancing the adhesion of cancer cells and reducing their migration and activity, which facilitates the growth of colorectal cancer cells that have metastasized to the liver." (PMID 37777749, 2023).
myocardial infarction (12 papers, 2019 to 2025). Gross necrosis of the myocardium, as a result of interruption of the blood supply to the area, as in coronary thrombosis. "As NET formation has two enzyme-based mechanisms: peptidyl arginine deiminase 4 and neutrophil elastase, here, we found that the formation of NETs is through the ROS-dependent and citrullinated histone H3-dominant pathway after myocardial infarction." (PMID 31249639, 2019). "The suppression of NETs by either inhibiting NADPH oxidase or inhibiting peptidyl arginine deiminase 4 might provide a new strategy to protect myocardial infarction injury in ApoE−/− mice." (PMID 31249639, 2019).
ovarian carcinoma (12 papers, 2009 to 2025). A malignant neoplasm originating from the surface ovarian epithelium. "PADI4 knockdown or PAD4 inhibitor treatment can effectively block NET formation and reduce omental implantation, providing new insight into improvements to the treatment of ovarian cancer and its common comorbidities." (PMID 36365233, 2022). "In ovarian cancer, an influx of neutrophils in the omentum was also observed before metastasis, and blockade of NET formation with peptidyl arginine deiminase 4 (PAD4), an enzyme that is essential for NET formation, could decease omental colonization of cancer cells." (PMID 32849640, 2020).
periodontitis (12 papers, 2018 to 2025). An acute or chronic inflammatory process that affects the tissues that surround and support the teeth. "The present study was the earliest to investigate possible associations between SNP rs2240340 in PADI4 gene and level 2 periodontitis." (PMID 33059697, 2020). "In periodontitis, increased expression of PADI2, PADI4, and citrullinated proteins accompanies the exacerbation of periodontitis." (PMID 37020554, 2023). "In the present study, the association of PADI4 and PADI2 SNPs with RA in individuals with self-reported periodontitis was investigated." (PMID 36076933, 2022). "And indeed, hypercitrullination accompanied with an increase in PADI4 expression at mRNA and protein level was proven in gingival connective tissue in the case of severe periodontitis." (PMID 33059697, 2020). "Associations between RA and SNPs in PADI4 were not statistically significant in the group with self-reported periodontitis (data not shown)." (PMID 36076933, 2022). "None of the examined SNPs in PADI2 (rs2057094, rs2076616, rs2235912 and rs1005753) or PADI4 (rs74058715, rs11203367, rs1748033 and rs2240335) were significantly associated with periodontitis per se (data not shown)." (PMID 36076933, 2022). "Investigating the importance of rs2240340 in PADI4 gene the T allele was proven to be associated with a higher susceptibility to RA comparing the total RA group to RA free controls without or level 1 periodontitis (p = 0.006)." (PMID 33059697, 2020). "Similarly, the mRNA levels of PADI2 and PADI4 were also increased in the gingival tissue of patients with periodontitis compared to healthy controls." (PMID 30064459, 2018). "Investigate the genetic variations of PTPN22, PADI4, and CTLA4 and their impacts on RA and periodontitis." (PMID 39811802, 2025). "The role of PADI polymorphism in periodontitis is not clear, but none of the PADI2 or PADI4 SNPs examined in this study associated with periodontitis." (PMID 36076933, 2022). "Having previously established that PADI4 SNPs associate with RA in the same cohort, we examined whether SNPs in either PADI2 or PADI4 associated with periodontitis in the non-RA control group." (PMID 36076933, 2022). "Similarly to the protein expression of PAD2 and PAD4, the mRNA expression of PADI2 and PADI4, assessed by qPCR analysis, was also significantly higher (p < 0.05 and p < 0.01, respectively) in the gingival tissue of patients with periodontitis compared to healthy controls without periodontitis." (PMID 30064459, 2018).
psoriasis (11 papers, 2010 to 2026). An autoimmune condition characterized by red, well-delineated plaques with silvery scales that are usually on the extensor surfaces and scalp. "Compared with WT mice, the deletion of Padi4 significantly reversed the psoriasis‐like symptoms caused by IMQ." (PMID 35281792, 2022). "The mRNA levels of psoriasis-related cytokines were measured via real-time reverse transcription polymerase chain reaction, and the effects of Cl-amidine, a peptidyl arginine deiminase 4 (PAD4) inhibitor, on psoriasis-like lesions were evaluated." (PMID 33214582, 2020). "In addition, imiquimod‐induced psoriasis‐like symptoms were remarkably ameliorated in peptidyl arginine deiminase 4 (PAD4) knockout mice, which cannot form NETs." (PMID 35281792, 2022).
viral infection (11 papers, 2011 to 2025). "On the other hand, reduced PADI4 levels may contribute to less active defences against viral infection, due to gene regulatory changes, changes in deimination of immune related proteins, or impaired NETosis in these individuals." (PMID 32629995, 2020). "Targeted analysis of MMP9 (matrix metallopeptidase 9), PADI4 (peptidyl arginine deiminase 4) and LTF (lactotransferrin) showed these to be elevated in MIS-C and bacterial infection in comparison with viral infection and KD." (PMID 39300098, 2024). "Neutrophil activation derived autoantigens (MPO, PRTN3, and PADI4) were prominently increased in blood of both SARS-CoV-1 and SARS-CoV-2 viral infections, while TSHR and PTPRN2 autoantigens were specifically increased in SARS-CoV-2." (PMID 34276672, 2021).
interstitial lung disease (10 papers, 2014 to 2023). A diverse group of lung diseases that affect the lung parenchyma. "We aimed to identify single nucleotide variants (SNV) in PADI2 and PADI4 genes (PAD2 and PAD4 proteins, respectively) associated with susceptibility to interstitial lung disease (ILD) in RA patients and the PAD2 and PAD4 levels." (PMID 37759458, 2023). "Therefore, PAD4/PADI4 could be a marker in interstitial lung diseases." (PMID 37759458, 2023).
leukemia (10 papers, 2010 to 2025). A malignant (clonal) hematologic disorder, involving hematopoietic stem cells and characterized by the presence of primitive or atypical myeloid or lymphoid cells in the bone marrow and the blood. "It is worth noting that PADI4 acts as a co-regulator of Tal1 in leukaemia, where it counteracts transcriptionally repressive histone arginine methylation via histone citrullination." (PMID 37778387, 2023). "Additionally, histone citrullination, mediated by peptidyl arginine deiminase 4 (PAD4), has been implicated in NETosis and studied in neutrophil-like human leukemia 60 (HL-60) cells." (PMID 40806591, 2025). "PADI4 is therefore a promising target for the treatment of leukaemia and our results indicate that targeting it may offer a therapeutic window." (PMID 35603697, 2022). "Histone citrullination is antagonistic to histone arginine methylation, a modification that has established roles in the regulation of haematopoiesis and PADI4 was previously shown to influence gene expression by counteracting arginine methylation in leukaemia cells." (PMID 35603697, 2022). "In addition, western blot analysis detected PADI4 expression in cultured tumour cell lines including A549 (lung adenocarcinoma), SKOV3 (ovarian adenocarcinoma), and U937 (leukaemia) cells." (PMID 20222985, 2010).
pulmonary fibrosis (10 papers, 2017 to 2025). Chronic progressive interstitial lung disorder characterized by the replacement of the lung tissue by connective tissue, leading to progressive dyspnea, respiratory failure, or right heart failure. "Targeted therapeutic strategies, such as NE inhibitors, peptidyl arginine deiminase 4 (PAD4) inhibitors, blockade of the C5a-C5aR1 axis, and stem cell therapy, present promising avenues for the treatment of pulmonary fibrosis." (PMID 41394824, 2025). "PADI4 ablation or DNase I administration protected mice against age related organ fibrosis, including pulmonary fibrosis." (PMID 29287593, 2017).
asthma (9 papers, 2021 to 2025). "NETs formation has been proven to be upregulated in asthma and has a tight connection with peptidyl arginine deiminase 4 (PADI4) and NOX." (PMID 37063888, 2023).
hepatocellular carcinoma (9 papers, 2009 to 2025). A malignant tumor that arises from hepatocytes. "Conversely, decreased PADI4 expression has recently been associated with global hypomethylation in hepatocellular carcinoma during hepatitis B virus exposure." (PMID 24957603, 2014).